IGFN1 (immunoglobulin like and fibronectin type III domain containing 1)
Synonyms: EEF1A2BP1; DKFZp434B1231
Tractability: No criterion of Open Targets' tractability assessment is met for any kind of drug.
Gene: Protein-coding gene on chromosome 1 (201,190,824 to 201,228,952, forward strand). Ensembl gene ENSG00000163395.
Subcellular location: Nucleus; Cytoplasm, myofibril, sarcomere, Z line
Subcellular location (Human Protein Atlas): Midbody ring
Gene Ontology:
Molecular function: protein binding
Cellular component: nucleus; Z disc
Genetic constraint (gnomAD): Loss-of-function variants: 240 observed, 267.85 expected, observed/expected ratio (o/e) 0.9, 90% interval 0.81 to 1. The upper end of that interval is the gene's LOEUF score, 1, which puts it in group 4 of 6, group 1 being the genes least tolerant of losing a copy. Missense variants: 4,375 observed, 4,380.3 expected, observed/expected ratio (o/e) 1, 90% interval 0.97 to 1.02. Synonymous variants: 1,678 observed, 1,677.1 expected, observed/expected ratio (o/e) 1, 90% interval 0.96 to 1.04.
Homologues: Orthologues: chimpanzee IGFN1 (95% identical), mouse Igfn1 (44% identical), rat Igfn1 (43% identical), macaque IGFN1 (31% identical), Drosophila melanogaster bt (21% identical), Caenorhabditis elegans unc-89 (7% identical), Caenorhabditis elegans unc-22 (7% identical), Caenorhabditis elegans dim-1 (2% identical). Paralogues in human: OBSCN (10% identical), HMCN1 (9% identical), SPEG (6% identical), MYPN (5% identical), ALPK3 (5% identical), PALLD (4% identical), CCDC141 (3% identical), MYOT (2% identical), SPEGNB (2% identical).
Diseases named in the same sentence as IGFN1 in open-access papers:
IGFN1 is named in the same sentence as 20 diseases in open-access papers, as found by Europe PMC text mining. Sharing a sentence is not in itself a finding about the gene and the disease. The quoted sentences say what the papers report.
renal cell carcinoma (3 papers, 2018 to 2022). "As for IGFN1, although the biological function of this gene remains unclear, IGFN1 expression has been associated with susceptibility to primary retroperitoneal liposarcoma and renal cell carcinoma, and the radiotherapy response in non-small cell lung cancer." (PMID 35456975, 2022). "Two novel splicing isoforms of IGFN1 have been identified in renal cell carcinoma (RCC), one with 5’exon extension and an isoform with a novel exon." (PMID 30335789, 2018). "The IGFN1 (Immunoglobulin-Like And Fibronectin Type III Domain Containing 1) gene is reported to have an impact on the formation of G-quadruplex structure so it could be targeted for therapeutic intervention in renal cell carcinoma." (PMID 35831825, 2022).
arteriovenous malformations (1 paper, 2016). "If the functions of Igfn1 and Krt18 are unknown in neurons, their function in smooth muscle cells and implication in intracerebral arteriovenous malformations indicate that hypergravity could act on pericytes to modify the cerebrovascular function and hippocampus perfusion." (PMID 28082866, 2016).
Duchenne muscular dystrophy (1 paper, 2011). Duchenne muscular dystrophy (DMD) is a neuromuscular disease characterized by rapidly progressive muscle weakness and wasting due to degeneration of skeletal, smooth and cardiac muscle. "In cultured myotubes, IGFN1 expression inhibited apoptosis and promoted cell proliferation in hyper-catabolic trauma patients and was required for the muscle-specific expression of utrophin A, a sarcomellar protein causal in the fatal neuromuscular disease Duchenne Muscular Dystrophy." (PMID 22194858, 2011).
glioma (1 paper, 2022). A benign or malignant brain and spinal cord tumor that arises from glial cells (astrocytes, oligodendrocytes, ependymal cells). "No published evidence was available as to the roles of the remaining eight underexpressed gene signatures (CHST9, CSDC2, ENHO, FERMT1, IGFN1, LINC00836, MGAT4C and SHANK2) regarding glioma pathogenesis or prognosis." (PMID 35456975, 2022).
neuroblastoma (1 paper, 2015). Neuroblastoma (NB) is the most common solid, extracranial childhood tumor. "Among the neuroblastoma genes, RAD54B, BBS9 and UNKL were detected in exosomes while BBS9, IGFN1 and PKD1L3 were identified in ectosomes." (PMID 25944692, 2015).
Polypoidal choroidal vasculopathy (1 paper, 2025). The presence of aneurysmal 'polypoidal' lesions in the choroidal vasculature. "Immunoglobulin like and fibronectin type III domain containing 1 (IGFN1) may play a role in skeletal muscle development and has been associated with polypoidal choroidal vasculopathy." (PMID 40957660, 2025).
ulcer (1 paper, 2025). "In our investigation, we identified the pro-inflammatory gene IGFN1 as significantly differentially expressed in both the diabetic and normal ulcer mouse models." (PMID 40620796, 2025).
cancer (3 papers, 2018 to 2025). A tumor composed of atypical neoplastic, often pleomorphic cells that invade other tissues. "This led to pSTAT3-mediated activation of cancer stemness genes (IGFN1, EML1, and SRGN), contributing to Adriamycin resistance." (PMID 40696387, 2025). "This study shows that IGFN1 alternative splicing changes with the treatment with PDS in UOK146 cell line, therefore IGFN1 splicing could be targeted as therapeutics in cancer and other diseases." (PMID 30335789, 2018).
tumor (1 paper, 2020). "In support, expression of SMAD2/3 target genes Cyr61 and Igfn1 is also reduced in the muscles of C26 tumor-bearing mice in response to TMEPAI expression." (PMID 33250771, 2020). "Phosphorylation of SMAD3 was significantly reduced in the presence of TMEPAI in the muscles of C26 tumor-bearing mice, and TMEPAI expression also attenuated transcriptional activation of SMAD2/3-target genes in C26 tumor-bearing mice, including Cyr61, and Igfn1." (PMID 33250771, 2020).
IGFN1 also shares sentences with these, for which no sentence is quoted: metastatic tumors (2 papers); Parkinson disease (2); Alzheimer disease (1); breast carcinoma (1); dengue (1); infection (1); neuromuscular disease (1); non-small cell lung carcinoma (1); prostate adenocarcinoma (1); schizophrenia (1); virus infection (1).